ERBB2 (erb-b2 receptor tyrosine kinase 2)
Diseases named in the same sentence as ERBB2 in open-access papers (continued):
Sharing a sentence is not in itself a finding about the gene and the disease.
mucinous ovarian cancer (23 papers, 2009 to 2025). An invasive malignant neoplasm that arises from the ovary and is characterized by the presence of malignant epithelial cells that contain intracytoplasmic mucin and may resemble the epithelial cells of the endocervix or gastrointestinal tract. "We identified several genes known to be mutated in ovarian mucinous carcinomas, including ERBB2, ARID1A, and CREBBP." (PMID 40981433, 2025). "Molecular aberrations noted in mucinous ovarian cancer that suggest a match with current targeted therapies include amplification of ERBB2 (26.7%) and BRAF mutation (9%)." (PMID 32679669, 2020). "Amplification of ERBB2 was observed in 8 of the 36 ovarian mucinous carcinomas and provides a potentially useful target for trastuzumab therapy." (PMID 40981433, 2025). "•We report marked response to carboplatin/paclitaxel/trastuzumab in recurrent ERBB2-amplified mucinous ovarian carcinoma." (PMID 37449085, 2023). "Ultimately, this case highlights the ongoing need for further prospective evaluation of targeted therapeutics in mucinous ovarian carcinoma with special attention paid to the identification and treatment of patients with ERBB2-amplified tumors." (PMID 37449085, 2023). "We describe durable remission in a 29-year-old woman with recurrent metastatic ERBB2-amplified mucinous ovarian adenocarcinoma following optimal secondary cytoreduction and carboplatin/paclitaxel/trastuzumab followed by one year of maintenance trastuzumab." (PMID 37449085, 2023). "The highest frequency of the ERBB2 gene overexpression was found in mucinous ovarian carcinoma, between 19% and 26.7%." (PMID 34439094, 2021). "Therapeutic agents targeting specific biomarkers and key molecular drivers of mucinous ovarian carcinoma such as ERBB2 and KRAS may exhibit promising results." (PMID 36603894, 2023). "Furthermore, the higher frequencies of amplification in ERBB2 reported in some studies of clear cell and mucinous carcinomas of the ovary suggest that anti-HER2 directed therapy may be more beneficial in these subgroups." (PMID 27983698, 2016). "Analyses of focal copy number changes revealed amplifications of CCND1 and ERBB2 and homozygous deletions of CDKN2A/B in mucinous ovarian carcinomas, a finding consistent with previous studies." (PMID 40981433, 2025). "ERBB2 (human epidermal growth factor receptor 2, HER2) gene amplification has been reported in approximately 20–30% of invasive mucinous ovarian cancers and 6% of mucinous borderline ovarian carcinomas." (PMID 29795040, 2018). "Overexpression/amplification of HER2 (ERBB2), a member of the epidermal growth factor receptor family that acts upstream of KRAS, has been identified in up to 35% of mucinous ovarian cancer cases." (PMID 27231561, 2015).
colon adenocarcinoma (22 papers, 2009 to 2025). "Furthermore, among the 19 cases of colon adenocarcinoma (12 cases with identified metastases) examined, only 1 (5.3%) exhibited an alteration in the ERBB2 gene that was associated with the initiation of therapy." (PMID 41515496, 2025). "In a study using colon adenocarcinoma cell line (CACO-2), complex forming of ErbB2 and MUC4 phosphorylates ErbB2 on tyrosine 1139 and 1248, and activated the downstream signaling pathway of p38 and Akt." (PMID 33217964, 2020).
ependymoma (22 papers, 2011 to 2025). A WHO grade II, slow growing tumor of children and young adults, usually located intraventricularly. "A study of a large cohort of pediatric ependymoma patients found that co-expression of ErbB4 with ErbB2 occurred in over 70% of cases and was associated with higher proliferative index and poorer patient survival." (PMID 36119496, 2022). "Co-expression of ErbB 2 (Her2) and ErbB 4 has been identified in over 75% of ependymomas, and ligand-dependent activation of the ErbB receptor induces cellular proliferation in cultured ependymoma cells." (PMID 38125233, 2023). "Lapatinib, an epidermal growth factor receptor inhibitor, was used because of its ability to inhibit both ErbB2 (human epidermal growth factor receptor 2) and ErbB1 (epidermal growth factor receptor), which are frequently overexpressed in ependymomas." (PMID 34885237, 2021). "We demonstrate that the Nf2 protein, merlin, negatively regulates spinal neural progenitor cell survival and glial differentiation in an ErbB2-dependent manner, and that NF2-associated spinal ependymomas exhibit increased ErbB2 activation." (PMID 24817309, 2014). "The rationale for combining TMZ with lapatinib relied on the fact that this treatment targets the epidermal growth factor receptor (ErbB1) and the related family member human epidermal growth factor receptor 2/neu (ErbB2), which are both overexpressed on ependymoma tumor cells." (PMID 39199553, 2024). "Lapatinib targets the epidermal growth factor receptors (ErbB1 and ErbB2), which may be expressed by ependymoma cells." (PMID 35384591, 2022). "Taken together, our findings demonstrate that ErbB2 is a critical regulator of Nf2-deficient SC NPC survival and glial differentiation, and support further evaluation in preclinical and human clinical trials for NF2-associated and select sporadic ependymomas." (PMID 24817309, 2014). "The new ependymomas indicated that TH34_1381_S01’s ERBB2 expression was not exceptional for ependymomas." (PMID 40119139, 2025). "Lapatinib is ErbB1 and ErbB2 inhibitors that can cross the blood–brain barrier; however, it was not specifically tested in ependymoma in vitro." (PMID 39679838, 2024).
B-cell lymphoma (21 papers, 2011 to 2025). "For example, Trastuzumab deruxtecan is an anti-ERBB2 antibody conjugated with topoisomerase inhibitor for NSCLC with HER2 mutation and an anti-CD20 antibody conjugated with a nanoparticle loaded with paclitaxel for B-cell lymphoma." (PMID 39596025, 2024).
colorectal adenocarcinoma (21 papers, 2006 to 2025). The most common type of colorectal carcinoma. "Somatic ERBB2 amplification or activating mutations occur in approximately 2-5% of metastatic colorectal adenocarcinomas and are presumed to be oncogenic drivers, but limited evidence exists to suggest these lesions are sensitive to targeted monotherapy in patients." (PMID 26244165, 2015). "In addition to atypical BRAF mutations, ERBB2/HER2 genomic alterations are also different when comparing duodenal SBAs to jejunal/ileal SBAs, and when comparing SBAs to gastric and colorectal adenocarcinomas." (PMID 35267592, 2022).
Hyperglycemia (21 papers, 2012 to 2026). An increased concentration of glucose in the blood. "For example, in the diabetic mesenteric vascular bed, hyperglycemia-induced upregulation of Akt signaling was prevented by lapatinib, a dual inhibitor of EGFR and ErbB2." (PMID 34408653, 2021). "Chronic treatment with AG825 or AG1478, selective inhibitors of erbB2 and EGFR respectively, did not affect hyperglycemia but led to an exacerbation whereas acute administration of the EGFR ligand, epidermal growth factor (EGF), led to an improvement in cardiac recovery in diabetic hearts." (PMID 22720029, 2012).
adenoma (20 papers, 2014 to 2025). A neoplasm arising from the epithelium. "Overexpression of Erbb2 in the basal epithelium of the mouse gallbladder resulted in the development of adenoma and progression to adenocarcinoma characterized by papillary structures, demonstrating a functional role of Erbb2 in gallbladder carcinogenesis." (PMID 29142904, 2017). "The expression levels of ErbB2 were comparable among adenomas and the normal epithelium." (PMID 29872037, 2018). "Notably, ErbB2 inhibition decreased the basal ERK activity less efficiently in adenomas or in GSK3 inhibitor-treated organoids than in normal organoids." (PMID 29872037, 2018). "In vivo images were collected from a spontaneous adenoma in the rectum of a live mouse using fluorescently-labeled peptides specific for Prdx1, EGFR, and ErbB2, respectively." (PMID 37945660, 2023). "We initially determined the steady-state expression of ERBB2 mRNA in the normal colon cell lines, CCD33 and CCD841, as well as the CRC adenoma cell lines HCT116 and HT29 using qRT-PCR." (PMID 36612126, 2022). "EGFR, a subtype of the ErbB receptors, which include EGFR (ErbB1, HER1), p185her2/neu (ErbB2, HER2), ErbB3 (HER3), and ErbB4 (HER4), can regulate cell motility and adhesion, adenoma invasion, angiogenesis, and adenoma cell proliferation." (PMID 31798535, 2019). "By K-means clustering, the expression levels of five genes, AKT1, BCL2L1, ERBB2, MTA2 and TNFRSF25, were seen to be significantly up-regulated (p <0.05) in LST-adenoma compared to Ip-adenoma." (PMID 26048755, 2015). "As a result of K-means clustering, the expression levels of five genes, AKT1, BCL2L1, ERBB2, MTA2 and TNFRSF25, were found to be significantly up-regulated (p < 0.05) in LST-adenoma, compared to Ip-adenoma." (PMID 26048755, 2015). "Her adenoma was positive for EGFR and ErbB2 on immunohistochemistry." (PMID 34867776, 2021). "More than 50% of prolactinomas express EGFR and 25% express ErbB2 protein (reviewed in, with 40% of invasive adenomas staining positive for ErbB2, compared to 1.2% of noninvasive adenomas." (PMID 34867776, 2021). "It is also noteworthy that autophosphorylation of ErbB2 was suppressed by ErbB2i, but not by EGFRi, in normal and adenoma organoids." (PMID 29872037, 2018).
intrahepatic cholangiocarcinoma (20 papers, 2008 to 2026). A carcinoma that arises from the intrahepatic bile duct epithelium in any site of the intrahepatic biliary tree. "Similar oncogenic drivers, including mutations in KRAS, BRAF, and HER2 (ERBB2), have been identified in intrahepatic cholangiocarcinoma (iCCA)." (PMID 41373672, 2025). "A 64-year-old male was diagnosed with advanced intrahepatic cholangiocarcinoma with ERBB2 (HER2) 3 + amplification determined by tissue-based testing and confirmed by next-generation sequencing." (PMID 36973682, 2023). "Moreover, ERBB2 signaling pathway enriched by SP1 and ELK1 has been implicated in the molecular pathogenesis of intrahepatic cholangiocarcinoma by interacting with other relevant signaling pathways, including linking to bile acid, vascular endothelial growth factor signaling." (PMID 24897108, 2014).
breast disease (19 papers, 2008 to 2024). "We herein show for the first time that the expression of the p140Cap adaptor protein is clinically relevant to the naturally occurring ERBB2-related breast cancer disease." (PMID 28300085, 2017).
salivary gland tumors (19 papers, 2010 to 2025). "The strongest antitumoral effect was achieved after two vaccinations and a dose of 108 pfu in BALB-neuT mice with transplanted salivary gland tumors cells overexpressing ErbB2/Neu." (PMID 32423101, 2020). "Salivary gland tumors are a group of heterogeneous lesions which express ErbB2, whose current treatment involves surgery and adjuvant radio(chemo)therapy." (PMID 24886178, 2014). "Recently, given that the high histopatological similarity between salivary ductal and breast carcinomas, Trastuzumab, a humanized monoclonal antibody to ErbB2, has been proposed as a potential therapy for salivary gland tumors treatment." (PMID 24886178, 2014). "We previously demonstrated that the intratumoral vaccination with a recombinant vaccinia virus encoding for ErbB2/Neu (rV-neuT) induced a strong antitumor response and antitumoral activity in mammary and salivary gland tumors overexpressing ErbB2/Neu in BALB-neuT mice." (PMID 32423101, 2020). "Trastuzumab, a monoclonal antibody to ErbB2, was proposed for salivary gland tumors treatment." (PMID 24886178, 2014). "The resulting candidate genes as possible therapeutic targets were FN1, SPP1, EGF, and ERBB2, and all those genes had been tested as a target in other neoplasm kinds but not salivary gland neoplasm." (PMID 36146635, 2022).
type 2 diabetes (19 papers, 2010 to 2026). "The role of ROCK as a downstream effector of EGFR/ErbB2 heterodimers was also confirmed recently in a mouse model of high-fat diet induced obesity/type 2 diabetes bearing vascular smooth muscle-specific deletion of EGFR." (PMID 34408653, 2021).
viral infection (19 papers, 2011 to 2025). "The results of the proteome analysis provide valuable insights into the cellular proteins and pathways associated with HPV16 entry and infection, with ErbB2 emerging as a potential player in facilitating viral infection." (PMID 38370412, 2024). "FMDV RNA copy numbers were significantly reduced in cells treated with 30 μM Lapatinib, indicating that inhibiting EGFR/ERBB2 tyrosine kinase activity and activation of this pathway can inhibit virus infection." (PMID 38512977, 2024). "The most enriched biological processes for the proteins with increased abundance in AdV-EVs included the GO terms representative of protein translation in response to viral infections, cytoskeletal remodeling, interactions with the extracellular matrix, and mTOR and ErbB2 signaling pathways." (PMID 41157572, 2025).
uterine cancer (18 papers, 2016 to 2025). Primary or metastatic malignant neoplasm involving the uterine corpus and/or the cervix. "The OCAv3 NGS assay offers a more time-, cost- and tissue-efficient method for simultaneously assessing POLE mutations and ERBB2 amplifications in uterine carcinomas, particularly in cases with limited tissue material." (PMID 39682116, 2024). "Both MYC and ERBB2 have likewise shown associations with uterine cancers in earlier studies." (PMID 29716549, 2018). "Additionally, we provided real-world data on the application of these panels in assessing ERBB2 amplification in different tumor types, including uterine carcinoma." (PMID 39682116, 2024). "The analytical performance of the OCAv3 NGS assay for detecting ERBB2 amplifications was benchmarked against the gold standard HER2 testing method, IHC-FISH, across two independent cohorts of uterine carcinomas." (PMID 39682116, 2024).
clear cell carcinoma (17 papers, 2010 to 2025). "Such ERBB2 gain was a hallmark of endometrioid and clear cell carcinomas (P = 0.036)." (PMID 33947352, 2021). "For RTK, the gene with the clearest actionability was ERBB2, with gain being observed in 3, 23 and 22% of patients with high-grade serous, endometrioid and clear cell carcinomas, respectively." (PMID 33947352, 2021). "ERBB2 was the only RTK that was deemed actionable in a considerable proportion of patients in our cohort, mostly in endometrioid and clear cell carcinomas." (PMID 33947352, 2021).
endometrioid carcinoma (17 papers, 2010 to 2026). "ERBB2 amplifications were more frequent in the mixed carcinomas groups (33%) compared to pure serous (11%) and pure endometrioid carcinomas (0%)." (PMID 41681911, 2026).
tubular adenocarcinoma (16 papers, 2013 to 2026). An infiltrating adenocarcinoma in which the malignant cells form tubular structures. "While nearly all mutant Kras-driven GBC were classified as tubular adenocarcinomas, mutant ERBB2-driven GBCs were mostly of papillary/tubulo-papillary differentiation." (PMID 31795490, 2019).